CDKN2B (cyclin dependent kinase inhibitor 2B)
Description:
Interacts strongly with CDK4 and CDK6. Potent inhibitor. Potential effector of TGF-beta induced cell cycle arrest.
Synonyms: p15INK4B; MTS2; P15; INK4B; TP15; CDK4I
Tractability: No criterion of Open Targets' tractability assessment is met for any kind of drug.
Gene: Protein-coding gene on chromosome 9 (22,002,903 to 22,009,305, reverse strand). Ensembl gene ENSG00000147883.
Subcellular location: Cytoplasm
Subcellular location (Human Protein Atlas): Nucleoplasm; Primary cilium transition zone; Cytosol; Primary cilium; Primary cilium tip
Pathways (Reactome):
Cellular responses to stimuli: Oncogene Induced Senescence; Oxidative Stress Induced Senescence; Senescence-Associated Secretory Phenotype (SASP)
Cell Cycle: Cyclin D associated events in G1
Signal Transduction: SMAD2/SMAD3:SMAD4 heterotrimer regulates transcription
Gene Ontology:
Molecular function: cyclin-dependent protein serine/threonine kinase inhibitor activity; protein binding; protein kinase binding
Biological process: cellular response to cell-matrix adhesion; cellular response to nutrient; cellular senescence; megakaryocyte differentiation; negative regulation of cell population proliferation; negative regulation of epithelial cell proliferation; negative regulation of G1/S transition of mitotic cell cycle; positive regulation of transforming growth factor beta receptor signaling pathway; regulation of G0 to G1 transition; transforming growth factor beta receptor signaling pathway; regulation of G1/S transition of mitotic cell cycle
Cellular component: cytoplasm; cytosol; nucleus
Genetic constraint (gnomAD): Loss-of-function variants: 8 observed, 6.93 expected, observed/expected ratio (o/e) 1.15, 90% interval 0.67 to 1.84. That is too few expected variants to judge how well the gene tolerates losing a copy. Missense variants: 244 observed, 197.35 expected, observed/expected ratio (o/e) 1.24, 90% interval 1.11 to 1.38. Synonymous variants: 93 observed, 88.57 expected, observed/expected ratio (o/e) 1.05, 90% interval 0.89 to 1.25.
Homologues: Orthologues: chimpanzee CDKN2B (100% identical), macaque CDKN2B (95% identical), rabbit CDKN2B (89% identical), pig CDKN2B (83% identical), dog CDKN2B (82% identical), mouse Cdkn2b (82% identical), guinea pig CDKN2B (81% identical), rat Cdkn2b (80% identical). Paralogues in human: CDKN2A (78% identical).
Diseases named in the same sentence as CDKN2B in open-access papers:
CDKN2B is named in the same sentence as 242 diseases in open-access papers, as found by Europe PMC text mining. Sharing a sentence is not in itself a finding about the gene and the disease. The quoted sentences say what the papers report.
glioma (51 papers, 2010 to 2025). A benign or malignant brain and spinal cord tumor that arises from glial cells (astrocytes, oligodendrocytes, ependymal cells). "The status of CDKN2A/CDKN2B homozygous deletion linked to the INTS9 expression was found only in the IDH mutant glioma, including IDH mutant astrocytoma and oligodendroglia." (PMID 37537630, 2023). "The CDKN2B region has been associated with other diseases such as gliomas, diabetes, and myocardial infarction, but the C allele of rs1063192, which reduces the risk of glaucoma, increases the risk for glioma." (PMID 22761751, 2012). "Furthermore, CDKN2A germline mutations are responsible for the melanoma-astrocytoma syndrome (MIM number 155755), and genetic variants close to both CDKN2A and CDKN2B genes (on the chromosomal locus 9p21) are known to increase the risk for glioma, basal cell carcinoma, and melanoma." (PMID 31968687, 2020). "Early cytogenetic studies identified recurrent loss of the short arm of chromosome 9 in glioma cell lines, many involving the 9p21 locus, which includes CDKN2A and CDKN2B." (PMID 37504251, 2023). "Currently, molecular markers for adult glioma classification and prognosis include IDH1/2 mutations, homozygous deletion of CDKN2A and/or CDKN2B, EGFR amplification, and TERT promoter mutation." (PMID 37214395, 2023). "Low expression of CDKN2B and SPOCK2 was associated with poor survival in glioma patients in the TCGA LGG/GBM dataset." (PMID 36973285, 2023). "Our results showed that the combined chromosome 7 gain/10 loss and TERT promoter mutation associated with high INTS9 in the IDH wildtype astrocytoma during the CDKN2A/CDKN2B homozygous deletion in the IDH mutant glioma." (PMID 37537630, 2023). "Our results showed that risk subclonal mutation correlated with the deletion of 9p21.3 (which contained CDKN2A and CDKN2B) in gliomas, especially in LGG." (PMID 35496054, 2022). "The rs4977756 is mapped 59 kb telomeric to CDKN2B within a 122-kb region of LD at 9p21.3, which encompasses the CDKN2A-CDKN2B tumor suppressor genes and was shown to be associated with the risk of glioma." (PMID 34648117, 2022). "Across brain tumor subtypes, such as glioblastoma and low-grade glioma, differences in mutation rates showed the same trend in eight driver events among C1/2 subtypes, including CDKN2A/CDKN2B and PTEN deletion, IDH mutation, and co-deletion of 1p and 19q." (PMID 34722280, 2021). "Our results showed the possible synergy of CDKN2A and CDKN2B HDs with BRAF mutations, especially in adult glioma patients with BRAFV600E and BRAFnon-V600E." (PMID 33980169, 2021). "Conversely, later-onset gliomas were associated with the IDHwt subtype paired with EGFR or MDM4 amplification, as well as with CDKN2A, CDKN2B, or PTEN deletion (FDR <0.015)." (PMID 34788626, 2021). "Three of these glioma-associated SNPs were pleiotropic: RTEL1 (rs1291209: allergic disease asthma hay fever or eczema), CDKN2B (rs6475604: coronary heart disease, glaucoma, vertical cup disc ratio), and PHLDA1 (rs1565765: atrial fibrillation)." (PMID 33495464, 2021). "For example, high-grade gliomas are associated with risk variants in RTEL1, CDKN2B, and TERT, while low-grade gliomas with IDH mutation-1p/19q codeletion are associated with risk variants in CCDC26 and PHLDB1 regions." (PMID 31968687, 2020).
glioma (continued). "The dysregulated ceRNA network driven by the deletion of CDKN2B was enriched in Epac1/Rap1 pathway, which was proved to be important in glioma cell death." (PMID 31719831, 2019). "Although, association with tumor grade was not analyzed in our study due to the small number of low grade glioma, we found two risk variants in the CDKN2A and CDKN2B regions associated with mutated IDH1." (PMID 26839018, 2016). "Variants in CDKN2B and RTEL1 are strongly associated with high-grade glioma while variants in CCDC26 and PHLDB1 are associated with low-grade glioma." (PMID 26839018, 2016). "The prognosis of gliomas is significantly affected by these molecular alterations, such as whether IDH1, IDH2, EGFR, CDKN2A, and CDKN2B are altered for adult‐type gliomas, and whether H3 K27 and H3 G34 are altered for pediatric‐type gliomas." (PMID 39804195, 2025). "The alterations of CDKN2B, KMT5B, MAP2K1, PIK3CA, and chr9p were associated with hemorrhage, and this may be due to the fact that most of them affect glioma cell proliferation and invasion." (PMID 38877400, 2024). "This characteristic CDKN2B downregulation may be useful in the future as both a biomarker to identify and a therapeutic strategy to treat early-stage gliomas in LFS patients." (PMID 36973285, 2023). "In 9p21.3, a recent transcriptome-wide association study (TWAS) in glioma only found CDKN2B but not its anti-sense transcript as candidate causal genes." (PMID 33936159, 2021). "Furthermore, amplification peaks of oncogenes (PIK3C2B, PDGFRA, EGFR, CDK4), and deletion peaks of tumor suppressor genes (TUSC1, CDKN2A, CDKN2B, PTEN, FAS, BNIP3) were detected in the gliomas with a high risk score." (PMID 32023222, 2020). "In addition to the integrated phenotypic and genotypic features of glioma, many genetic studies have found that common inherited variants near several genes (TERC, TERT, EGFR, CDKN2B, PHLDB1 and RTEL1) are associated with increased risk of adult glioma." (PMID 30462709, 2018). "In addition, PCNSHS and glioma may also show overlapping molecular features, such as BRAF V600E mutation or BRAF gene fusion, CDKN2A/CDKN2B homozygous deletion, etc." (PMID 40231251, 2025). "Functional analysis of CDKN2B through its influenced ceRNA network further revealed that the dysregulation of specific ceRNA networks driven by CNVs could act as prognostic markers of glioma." (PMID 31719831, 2019). "A case-control study recruited 855 high-grade glioma patients from four different geographic regions of the US and belonging to five inherited glioma risk variants: 5p15.3 (TERT), 8q24.21 (CCDC26/MLZE), 9p21.3 (CDKN2B), 11q23.3 (PHLDB1/DDX6) and 20q13.3 (RTEL1)." (PMID 30909395, 2019). "Within IDHwt gliomas, the significant CNAs observed in lower grade and GBM tumors were generally very similar, including gain of entire copies of chromosome 7, loss of entire copies of chromosome 10, and focal losses at chromosome 9 around the CDKN2A/CDKN2B locus." (PMID 26091668, 2015). "The expression of YTHDF2 was negatively correlated with CDKN2B and SPOCK2 mRNAs in multiple pediatric glioma datasets, supporting the pathological role of YTHDF2 negatively regulating CDKN2B and SPOCK2 transcripts in glioma development." (PMID 36973285, 2023). "We found that in adult glioma patients, BRAFV600E and BRAFnon-V600E frequently co-occurred with CDKN2A HDs combined with CDKN2B HDs, especially in patients with BRAFV600E." (PMID 33980169, 2021). "The first germline studies identified a locus on chromosome 9p21, encompassing the CDKN2A (MIM number 600160) and CDKN2B (MIM number 600431) tumor suppressor genes, which have an established role in glioma development." (PMID 31968687, 2020).
glioma (continued). "By performing a systematic analysis of the CNV-driven ceRNAs with clinical features, we found that the CNVs of some genes (such as MTAP/CDKN2A/CDKN2B/KLHL9) had significant impacts on histological diagnosis and survival in glioma." (PMID 31719831, 2019). "Meanwhile, higher levels of RhoA, another ceRNA member of CDKN2B and a downstream factor in TGF-β/MAPK signaling pathway, can significantly promote glioma cell proliferation and migration." (PMID 31719831, 2019). "Although IDH-mutant gliomas had lower RB1 expression along with higher methylation, the expression of RB pathway genes CDKN2A and CDKN2B was maintained." (PMID 27852048, 2017). "Genetic aberrations associated with worse prognoses, such as PDGFRA amplification, CDKN2A or CDKN2B deletion, and CDK4 amplification, may lead to further glioma subdivision." (PMID 38672625, 2024). "In contrast, copy number analysis of her DIPG revealed copy number changes frequently seen in gliomas including homozygous loss of RB1, SETDB2, CDKN2A and CDKN2B with no abnormalities in chromosome 17, distinguishing it from the primary medulloblastoma." (PMID 30049282, 2018). "Our previous study has shown that a panel of 12 genes including ERCC1, hMLH1, ATM, CDKN2B (p15INK4B), p14ARF, CDKN2A (p16INK4A), RASSF1A, RUNX3, GATA6, NDRG2, PTEN, and RARβ might be useful in evaluation of glioma aggressiveness." (PMID 25648363, 2015). "Interestingly, CDKN2B, CDKN2A, MTAP, and KLHL9 also belonged to the largest community in the dysregulated ceRNA network, suggesting their possible role to inhibit the development of glioma together." (PMID 31719831, 2019). "In glioma, genome-wide association studies have identified common genetic variations in 7 genes that increase glioma risk (TERT, EGFR, CCDC26, CDKN2A, CDKN2B, PHLDB1 and RTEL1) but BRCA1 is not among them and there is no known association between BRCA1 gene and glioblastoma multiforme (GBM)." (PMID 25880076, 2015).
melanoma (42 papers, 2005 to 2026). A malignant, usually aggressive tumor composed of atypical, neoplastic melanocytes. "For example, FOXC2-AS1 promotes melanoma cell proliferation by silencing the tumour suppressor gene cyclin-dependent kinase inhibitor 2B CDKN2B (which encodes p15INK4b) through an EZH2-dependent recruitment mechanism." (PMID 41463281, 2025). "Particularly, germline whole gene deletions of CDKN2A and CDKN2B are known to be associated with familial syndromes predisposing to malignant melanoma as well as other nervous system tumors, including meningioma, astrocytoma, and schwannoma." (PMID 35723634, 2022). "The study also suggests that loss of P14ARF has an additional role in melanoma relapse and possibly also a role for CDKN2B coded by CDKN2B." (PMID 20140953, 2010). "Further investigations are needed to clarify the role of CDKN2B in melanoma disease and how the variants affecting the gene could be related to melanoma risk." (PMID 23816148, 2013). "The additive role of CDKN2B and other contiguous genes might contribute to the development of melanoma, since p15 expression encoded by CDKN2B has been shown to differentiate nevus from melanoma." (PMID 40046620, 2025).